CXCR4 (C-X-C motif chemokine receptor 4)
Diseases named in the same sentence as CXCR4 in open-access papers (continued):
Sharing a sentence is not in itself a finding about the gene and the disease.
cancer (continued). "Interestingly, the content of CD133 + CXCR4+ cells in HCT116 cancer cells and RKO cells treated by 5-Fu/P85 copolymer micelles was decreased." (PMID 26864651, 2016). "Previous reports suggested that the CXCR4/CXCL12 signaling-mediated chemotaxis may be involved in migration of CXCR4+ cancer cells towards an increasing gradient of CXCL12 across vascular wall." (PMID 26993780, 2016). "Therefore, most of its anti-cancer activity is possibly mediated by direct binding to CXCR4 and interference with the interaction to its ligand (CXCL12)." (PMID 26646452, 2016). "The secretion of C–X–C motif chemokine 12 (CXCL12), also known as stromal-derived factor 1 (SDF-1), by stromal cells in the bone marrow is known to attract osteotropic cancer cells via stimulation of the C–X–C chemokine receptor type 4 (CXCR4) receptor that is up regulated by many tumors." (PMID 27618899, 2016). "A link between CXCR4 and cancer, in particular metastatic breast cancer, has been reported." (PMID 26744352, 2016). "The activation of caspase-3 activity leads to cancer cells apoptosis, and survivin overexpression promotes the growth and drug resistance of cancer cells; Moreover, CXCR4 and MMP2/9 expression may play critical roles in promoting metastasis of HCC cells." (PMID 27716619, 2016). "Targeting CXCR4 has shown therapeutic promise in preclinical models of various cancers." (PMID 26848769, 2016). "Consequently, CXCR4KO Jeko cells were more sensitive to LDE225 compared to parental cells, supporting that both CXCR4 signaling and oxidative stress induced signals are involved in autophagy induction to promote cancer cell survival." (PMID 26885608, 2016). "Preclinical data have validated CXCR4 as a potential target for anti-cancer drug development." (PMID 26954567, 2016). "In addition, synthetic polycationic viologen dendrimers (VGD) targeting CXCR4 were also developed to facilitate targeted delivery of plasmid DNAs and cancer therapy." (PMID 27173676, 2016). "Therefore, the CXCL12/CXCR4 axis contributes to the establishment of an appropriate microenvironment in the bone, or a “pre-metastatic niche”, for osteotropic cancers like breast, and prostate." (PMID 27618899, 2016). "Interestingly, halofuginone was also able to inhibit the ability of TGF-β to stimulate ANGPTL4 and CXCR4 expression, two factors identified as key players to prime cancer cells for metastasis respectively towards the lungs and towards the bones or the lungs." (PMID 26015407, 2015). "Metastasis and growth of many cancers is driven by CXCL12 through CXCR4 and may be modulated by DPPIV-mediated CXCL12 degradation." (PMID 26552750, 2015). "Conversely, CXCR4 was detectable in the majority of the cancer cell lines." (PMID 26020117, 2015). "Consistent with previous reports, we showed that PD of diffuse-type GC cells was mediated functionally by CXCR4 activation, which may lead to the chemoattractive invasion of free cancer cells to SDF-1-expressing mesothelium." (PMID 26110809, 2015). "However, despite the importance in the modulation of CXCR4-mediated signaling and cancer cell metastasis, the regulatory mechanism of CXCR7 expression has not been fully elucidated, either." (PMID 26413813, 2015). "Moreover, if CXCR4 was merely an early marker, it would be more likely to occur just the time of onset of cancer." (PMID 25669980, 2015). "Therefore, CXCR4 is an attractive target since it is the most common chemokine receptor expressed in cancer cells and correlates factors related to angiogenesis." (PMID 26318034, 2015). "The SDF-1/CXCR4 signaling axis participates actively in cancer metastasis." (PMID 25557170, 2015). "Inhibiting the SDF-1α and CXCR4 interaction may be a potential therapeutic approach for treating radiation-induced cancer cell invasion during radiotherapy for malignant tumors." (PMID 25843954, 2015).
cancer (continued). "In the ex vivo culture of the metastasized cancer cells, the expression level of CXCR4 was increased, and in the xenotransplantation of ex vivo cultured cancer cells, the expression level of CXCR4 was again decreased in the metastasized cancer cells in the lung." (PMID 26083776, 2015). "However, our meta-analysis supports the ongoing research that identified CXCR4-initiated signalling pathways as potentially druggable targets in cancer therapies." (PMID 26091099, 2015). "However, it is noteworthy that this ligand is known to be expressed in peritoneal mesothelial cells and to function as a chemokine to induce distant metastasis through an interaction with CXCR4-expressing cancer cells." (PMID 26110809, 2015). "Taken together these data suggest that IL-1β and IL-1R1 promote cancer growth and metastasis by up-regulating CXCR4 expression and that CXCR4 may be a link between inflammation and cancer." (PMID 26176534, 2015). "High nuclear and cytoplasmic CXCR4 expression was detected in cancer cells." (PMID 26161302, 2015). "Moreover, CXCR4 has also been found to be a prognostic marker in multiple cancers including melanoma, colon cancer, leukemia, breast cancer, and gliomas." (PMID 26030674, 2015). "Although what leads to the overexpression of CXCR4 in cancer cells remains unclear, studies point to genetic and microenvironmental factors." (PMID 25503960, 2015). "Also, CXCR4 has been under intensive investigation in the area of cancer and different auto-immune diseases such as rheumatoid arthritis and systemic lupus erythematosus." (PMID 26347749, 2015). "VEGF expression has been found to be more pronounced in CXCR4 expressing cancer cells." (PMID 26318034, 2015). "Thus, incorporating IL-24 with SDF-1/CXCR4-targeted therapies will be effective in controlling cancer cell metastasis." (PMID 25775124, 2015). "In addition, these findings also indicate that the increase of the expression level of CXCR4 requires a certain amount of time and optimal cancer cell density." (PMID 26083776, 2015). "In addition, CXCR4 is now known to be critical in almost all aspects of cancer biology, including proliferation, apoptosis, invasion, metastasis and angiogenesis." (PMID 25544759, 2015). "CXCR4 is proposed to regulate the tissue-specific metastasis in many cancers." (PMID 25774696, 2015). "In addition, we showed here that the inhibition of CXCR4 further enhanced the dormancy of the metastasized cancer cells in the lung." (PMID 26083776, 2015). "CXCR4 is also expressed in many types of cancer, and plays important roles in cancer metastasis." (PMID 26176534, 2015). "In addition, the expression level of CXCR4 was increased in the dormant cancer cells by the ex vivo culture, and the induction required a long period of culture duration and a high increase of the cell density." (PMID 26083776, 2015). "In addition, mitogen-activated protein kinase pathway (MAP kinase pathway) is another signaling pathway regulated by CXCR4 that promotes proliferation and survival of cancer cells." (PMID 27429863, 2015). "The CXCR4/CXCL12 axis can coordinate metastasis of a variety of cancers." (PMID 25888626, 2015). "Thus, several clinical studies to evaluate the efficacy of CXCR4 antagonists in cancer patients have been initiated, some of which are still ongoing." (PMID 26259237, 2015). "CXCR4 overexpression correlated with an advanced cancer stage and metastasis." (PMID 25605248, 2015). "CXCR4 expression levels have been shown to be very heterogeneous in various cancer types." (PMID 25774696, 2015). "In addition, the proliferation of the metastasized cancer cells was further decreased by the CXCR4 antagonist administration." (PMID 26083776, 2015). "The axis of CXCL12/CXCR4 has been considered to play an important role for cancer cell migration." (PMID 26078947, 2015).
cancer (continued). "CXCR4 is a seven transmembrane, G protein-coupled receptor widely expressed in various cell types, including lymphocytes, hematopoietic stem cells, endothelial and epithelial cells, and cancer cells." (PMID 25544759, 2015). "The pro-inflammatory cytokines TNF-α and IL-1β are also involved in the regulation of CXCR4 in human astroglioma cells, suggesting that inflammation may promote cancer development via CXCR4." (PMID 26176534, 2015). "Moreover, treatment with transforming growth factor-β enhanced the anti-cancer effect of docetaxel via induction of cell differentiation/asymmetric cell division of the CXCR4-positive gastric CSCs even in a dormant state." (PMID 26110809, 2015). "Thus, the CXCL12-CXCR4 biological axis formed by CXCL12 and its specific receptor CXCR4 plays an important role in the process of metastasis of cancer cells." (PMID 25866764, 2015). "Similarly, CXCR4 influences trafficking of other cell types such as lymphocytes and neutrophils, but also CXCR4-positive cancer cells." (PMID 26347749, 2015). "For this reason, the use of CXCR4 inhibitors is a new promising approach in cancer treatment." (PMID 26259237, 2015). "Pharmacological inhibition of Notch signaling reversed the up-regulation of CXCR4 induced by IL-1β, suggesting that Notch signaling may be involved in the growth and metastasis of cancers via up-regulation of CXCR4." (PMID 26176534, 2015). "Among many effects, SDF-1α/CXCR4 interaction regulates cancer cell motility and adhesion." (PMID 26231656, 2015). "Cancer cells expressing CXCR4 metastasize to tissues that highly produce SDF-1 including bone marrow; MM cells express CXCR4 and migrate to the bone marrow niche where interaction with osteoclasts and bone marrow stroma cells enhances MM cell survival and proliferation." (PMID 26384349, 2015). "Thus, disruption of the SDF-1/CXCR4 axis is likely to reduce metastasis, making this is promising target for cancer treatment." (PMID 25775124, 2015). "Besides HMGA2 and CXCR4, the expression of several other genes have also been shown to be important in the bone metastatic phenotype of cancer cells." (PMID 25909161, 2015). "CXCL12 signaling through CXCR4 also plays critical roles in cancer metastasis." (PMID 25773070, 2015). "Thus, we propose that loss of Rb or breakdown of this pathway primes cancer cells for metastatic transformation by allowing for the over-expression of pro-metastatic factors such as PLOD2 and CXCR4." (PMID 24919196, 2014). "On the one hand, CXCR4 is most commonly found in malignant cells from different types of cancer." (PMID 24475985, 2014). "Thus CXCR4 is an important therapeutic target for stroke, inflammation, neuromodulation, cancer, and in the prevention of HIV infection." (PMID 24808825, 2014). "Role of CXCR4 in metastatic process has been analyzed in many cancers." (PMID 24859274, 2014). "It should be noted that CXCR4 is expressed in multiple cell types in the immune and central nervous systems, hematopoietic stem/progenitor cells, endothelial and epithelial cells and cancer cells." (PMID 25216273, 2014). "Taken together, they deduced that SDF-1/CXCR-4 may interact in ligand-receptor style leading to chemotaxis that SDF-1 would direct CXCR-4 positive cancer cells to lymph nodes with high concentration of SDF-1." (PMID 24587996, 2014). "By inhibition of CXCR4, the growth and invasion of cancer cells can be impaired." (PMID 25471741, 2014). "We did not observe ligand-dependent recruitment of the corepressor SMRT to the CXCR4 promoter and are currently investigating the role of other nuclear cofactors required for AHR-mediated suppression of CXCR4 and other genes in cancer cells treated with omeprazole." (PMID 25011475, 2014). "Involvement of SDF-1α/CXCR4 in cancer progression is increasingly being appreciated." (PMID 25114911, 2014). "Indeed, there are many evidences of the essential role of CXCR4 in the enhanced invasion of several types of cancer." (PMID 24906407, 2014).
cancer (continued). "As a conclusion, agents interacting at CXCR4 could be useful to treat cancer as well as HIV infection." (PMID 24808825, 2014). "Considering the findings that the phosphorylation of CXCR4 at serine 339 may be a way to activate CXCR4 on the cells, our data further confirmed that CXCR4 shRNA could effectively inhibit CXCR4 function in IHCC cancers." (PMID 25471741, 2014). "Since we provide evidence of how chemotherapeutic drugs may alter CXCR4 expression, it may be an attractive approach to combine conventional therapy with antibody-based targeted therapies for cancer." (PMID 25514788, 2014). "CXCR4 is expressed in most cancer cells, and hypoxia and injury stimulate its production." (PMID 24647809, 2014). "The importance of CXCR4 has also been studied in the context of cancer." (PMID 25251539, 2014). "CXCR4 is hypothesized to be involved in cancer invasion and metastasis, and higher levels of this receptor are associated with higher grades and poor prognosis of cancer." (PMID 24944647, 2014). "Notably, most cancer stem cells (CSCs) express CXCR4 and respond to a chemotactic gradient of SDF-1, suggesting that CSCs most likely represent a subpopulation capable of initiating metastasis." (PMID 25536052, 2014). "Preclinical cancer models have revealed that directed metastasis of cancer cells is mediated by CXCR4 activation and migration of cancer cells is towards CXCL12 expressing organs while targeting CXCR4 impairs the spread of cancer cells and development of metastasis." (PMID 25471741, 2014). "It has been previously demonstrated that CXCR4 is frequently upregulated in cancer." (PMID 25114911, 2014). "Source of SDF-1α (autocrine or paracrine) and its interaction with CXCR4 may determine further signaling and its role in cancer progression." (PMID 25114911, 2014). "The CXCR4 signaling pathway is crucial in modulating cancer cell migration." (PMID 25120692, 2014). "CXCR4 has previously been highlighted for its role in cancer metastasis." (PMID 24944647, 2014). "The following-up studies also found that CXCR4 can mediate the metastasis of a variety of cancers." (PMID 25471741, 2014). "Moreover, CXCR4-positive cancer cells can migrate toward distant organs in response to CXCL12 gradient." (PMID 25471741, 2014). "The prevailing model of cancer metastasis is that malignant tumors spread to distant tissues through the over-expression of CXCR4, thereby sensitizing malignant cells to spread in response to distant gradients of CXCL12 produced by metastatic destination organs." (PMID 24594697, 2014). "Several studies showed high expression of SDF-1/CXCR4 in many cancers, including NPC." (PMID 24877105, 2014). "Among the chemokines, CXCL12, also known as stromal cell derived factor-1 (SDF-1), and its cognate receptor CXCR4 have been involved in cancer metastasis of several cancers where the CXCL12-CXCR4 axis is known to modulate phenomena such as chemotaxis, migration, proliferation, and angiogenesis." (PMID 25580125, 2014). "CXCL12/CXCR4 signaling has been shown to activate a number of downstream signaling molecules, which are involved in the regulation of growth, aggressive phenotypes and therapy resistance in cancer cells." (PMID 25359780, 2014). "The expressions of EpCAM, CD24, CD44, CD133, and CXCR4 antigens were membranous in carcinoma cells." (PMID 25240521, 2014). "Since SDF-1/CXCR4 is one of the major signaling axes of endothelial tubule formation and migration, especially in cancer, it is essential that we gain a better understanding of this phenomenon via αvβ3 and the signaling pathway that mediates radiation-inducible resistance." (PMID 23381805, 2013). "Although an association between mGluR5 and the SDF-1/CXCR4 system has not been reported in cancer cells, Luo and colleagues have demonstrated the induction of mGluR5 on E14.5 neural precursor cells by stimulating with SDF-1." (PMID 24236200, 2013).
cancer (continued). "Moreover, blockade of CXCR4 with monoclonal antibodies or targeted drugs reduces cancer burden and metastasis." (PMID 24278179, 2013). "Results from studies with animal models suggest that, in many cancers, CXCR4 is an important therapeutic target and that CXCR4 antagonists may be promising treatments for primary cancers and for metastases." (PMID 25285238, 2013). "Of course, peptide based CXCR4 antagonists are difficult to deliver orally, a route that could be favoured for treatment of cancer metastasis that require repeat dosing especially in an outpatient setting." (PMID 24205302, 2013). "A close relationship between PGK1 and the CXCR4/SDF1 axis is known for several cancers." (PMID 24376734, 2013). "Furthermore, L. acidophilus induced a decrease in mRNA expression of stromal-derived factor-1 receptor, CXCR4, suggesting a role in cancer metastasis prevention; on the down side however, also suppressed MHC-class I expression." (PMID 23760057, 2013). "Distant organs produce SDF1, whereas invasive cancer cells acquire CXCR4, a receptor of SDF1." (PMID 23296269, 2013). "Hence, several therapeutics for cancer cell metastasis have been designed to antagonize CXCR4-mediated signaling." (PMID 23468933, 2013). "If the downstream target gene(s) of SDF-1/CXCR4 system specifically expressed in cancer cells were identified, it is expected that anti-metastatic therapy might be performed more safely and effectively." (PMID 24236200, 2013). "Therefore cancer metastasis appears to depend on CXCR4 and the signalling occurring downstream of this receptor." (PMID 23320409, 2013). "CXCR4 is recognized as the most commonly expressed receptor on many types of cancer cells." (PMID 23381805, 2013). "Furthermore, we previously demonstrated that RhoE participates in hypoxia- induced EMT, a key process that contributes to cancer metastasis, in which CXCR4 is also involved." (PMID 24312338, 2013). "By contrast, RhoE might bind to CXCR4 and mediate downstream signal transduction, which might finally result in cancer metastasis." (PMID 24312338, 2013). "Furthermore, CXCR4-targeting metastasis suppressive treatment strategies with CXCR4 antagonists in experimental metastasis models of OS and in a wide range of other cancer metastasis models were only partially successful." (PMID 24040160, 2013). "CXCR4 is widely detected in human cancers of epithelial, mesenchymal and haematopoietic origin." (PMID 24205302, 2013). "Cancer progression appears to be dependent on SDF-1α/CXCR4 signaling." (PMID 23472069, 2013). "Although the levels of CXCR4 expression correlate directly and strikingly with the degree of metastasis in NPC and in several human carcinomas, the functional role of tyrosine sulfation of CXCR4 in these tumors is largely unknown." (PMID 23472069, 2013). "Moreover, the upregulation of CXCR4 has frequently been observed in various cancers, including colon carcinoma, lymphoma, breast cancer, glioblastoma, leukemia, prostate cancer, MM and pancreatic cancer." (PMID 23251606, 2012). "CD133+/CD44+/CXCR4+ cells represent a highly tumorigenic subset of cancer progenitors and targeting CXCR4 signaling may be beneficial in eliminating this subpopulation." (PMID 22359577, 2012). "However, the reason cancer cells that have undergone EMT have a higher expression of CXCR4 is far from clear." (PMID 22871210, 2012). "Hence, future studies are essential to establish not only the role of ubiquitination processes in CXCR7-related cancer progression but also the potential of therapies targeting the blockade of CXCR7 in cells in which it is co-expressed with CXCR4." (PMID 22457824, 2012). "Several different chemokine receptors (CR), including CXCR4, CCR7, CCR9 and CCR6, have been suggested to mediate metastasis to specific target-organs and the presence of a specific CR on cancer cells has been associated with a definite metastatic pattern." (PMID 22433180, 2012).